NDN (necdin, MAGE family member)
Diseases named in the same sentence as NDN in open-access papers (continued):
Sharing a sentence is not in itself a finding about the gene and the disease.
tumor (13 papers, 2012 to 2024). "NDN is a member of the melanoma-associated antigen family and serves as a candidate tumor suppressor gene to facilitate the entry of the cell into cell cycle arrest in multiple tumors, including CRC30." (PMID 35589723, 2022). "Loss of imprinted tumor suppressor function for NDN, DIRAS3 and PEG3 might permit growth of cancer cells in culture." (PMID 26689988, 2016). "To further investigate the in vivo role of Notch in E75-induced tumor malignancy, we inhibited Notch activation by expressing a dominant negative form of Notch (NDN)." (PMID 39516282, 2024). "NDN affects tumor cell proliferation in CRC by inhibiting the expression of LRP6, which is a key factor in the activation of the Wnt signaling pathway." (PMID 28521288, 2017). "A decrease in NDN expression was also observed in surgically resected CRC tissues (T) compared with their matched non-tumor tissues (N) using Western blot and qRT-PCR analyses." (PMID 28521288, 2017). "For the 43 paired normal and tumor tissue samples, the average percentages of methylation for CpG 1 and 2 in the NDN promoter in normal tissues were 36% and 42%, respectively." (PMID 26689988, 2016). "While several studies implicate NDN as a possible tumor suppressor, the mechanism behind its role in metastasis is unclear." (PMID 26384308, 2015). "Several studies have reported that NDN plays a tumor-suppressing role in various tumors." (PMID 35333696, 2022). "Furthermore, the over-expression of NDN inhibited cell proliferation in vitro and tumor growth in vivo by leading cell cycle arrest." (PMID 28521288, 2017). "Here, we test the hypothesis that specific candidate gene methylation markers (CCNA1, NDN, CD1A, DCC, p16, GADD45A) are associated with tumor recurrence and survival, in a well-characterized, prospective, cohort of 346 HNSCC patients." (PMID 26518708, 2015). "Furthermore, bioinformatics analysis showed that an anti-tumor protein, necdin (NDN), might be a potential target by miR-200c." (PMID 35333696, 2022). "These evidences indicated that NDN might be a tumor suppressor." (PMID 28521288, 2017). "Except for MGP, NDN,63SERP2,64FSTL1,65 and CDH566 were also closely related to tumor stemness." (PMID 38168907, 2024). "In agreement with the analytical results from the published CRC microarray dataset, the markedly decreased expression of NDN was observed in 65.5% (55/84) CRC tumor tissues compared with that in adjacent non-tumor tissues." (PMID 28521288, 2017). "Samples where RFLPs were present in the lymphocyte DNA sample but absent or with an altered ratio in the tumor sample were considered to exhibit LOH in the regions of 8 imprinted genes (H19, IGF2, KCNQ1, LIT1, GTL2, PEG1, PEG3 and NDN)." (PMID 22443985, 2012).
cancer (7 papers, 2012 to 2024). A tumor composed of atypical neoplastic, often pleomorphic cells that invade other tissues. "Previous studies have demonstrated that NDN is one of the genes silenced through deletion, maternal uniparental disomy or translocation in Prader-Will syndrome (PWS), and the promoter hypermethylation contributes to the down-regulation of NDN in cancer." (PMID 28521288, 2017). "To identify mechanisms by which NDN is downregulated, we genotyped 5 single nucleotide polymorphisms (SNPs) along NDN's coding region and 3′-UTR in the same 43 paired normal and cancer samples." (PMID 26689988, 2016). "It has been hypothesized that the lack of NDN in patients with PWS may lead to cancer predisposition." (PMID 37575996, 2023). "Although NDN is down-regulated in many types of cancers, the regulatory mechanism remains unclear." (PMID 28521288, 2017). "Many of these genes have previously been reported in cancer and also in the context of NB including NNAT, RB1, MAGEL2, GPR1, NDN." (PMID 39217334, 2024). "We also identified the upregulation of DAZL and ANXA3 (data not shown), genes previously reported to be induced by 5-aza-dC, NDN, reported to be imprinted, and MT1G, reported to be methylated in other cancers." (PMID 22984426, 2012). "NDN, where LOM was observed in 50% and intermediate LOM in 26% of NB samples, is involved in permanent growth arrest in post-mitotic neurons during the nervous system development and is downregulated in several cancers." (PMID 39217334, 2024). "An increase in the percentage of OCT4A-positive cells in tumors, in which the NDN was >1, may suggest a stimulating effect of the OCT4A phenotype on the differentiation process of cancer cells." (PMID 25216339, 2014).
neurodegenerative disease (1 paper, 2014). A disorder of the central nervous system characterized by gradual and progressive loss of neural tissue and neurologic function. "Comparison with aging brain data (3 patient cohorts, 221 samples) revealed 53 of these to be unique to neurodegenerative disease, many of which are strong candidates to be important in neuropathogenesis (e.g. NDN, NAP1L2)." (PMID 25187168, 2014).
NDN also shares sentences with these, for which no sentence is quoted: autism (3 papers); neurodevelopmental disorder (3); cognitive delay (2); Bardet-Biedl syndrome (1); bladder cancer (1); breast tumors (1); cryptorchidism (1); esophagus cancer (1); fetal growth restriction (1); head and neck squamous cell carcinoma (1); Kabuki syndrome (1); Koolen-de Vries syndrome (1); lymphedema (1); mental retardation, X-linked syndromic, Lubs type (1); metabolic disorders (1); Müllerian agenesis (1); neurological disorders (1); Noonan syndrome (1); prostate carcinoma (1); Rett syndrome (1); schizophrenia (1); Smith-Magenis syndrome (1).